IGF2BP2 (insulin like growth factor 2 mRNA binding protein 2)
Diseases named in the same sentence as IGF2BP2 in open-access papers (continued):
Sharing a sentence is not in itself a finding about the gene and the disease.
pancreatic cancer (continued). "For example, the m6A reader, insulin-like growth factor 2 mRNA binding protein 2 (IGF2BP2), regulates the stability of differentiation antagonizing non-protein coding RNA (DANCR), which is crucial for pancreatic cancer cell growth and tumorigenesis." (PMID 34065036, 2021). "In the oncomine database, expression of KIAA1429, LRPPRC, IGF2BP2, IGF2BP3, and EIF3H was higher in pancreatic cancer than normal tissues." (PMID 34332578, 2021). "The IGF2BP1 mRNA expression level was not upregulated in pancreatic cancer, but the IGF2BP2 and IGF2BP3 mRNA expression levels were upregulated in pancreatic cancer to varying degrees." (PMID 33246429, 2020). "The Compared with adjacent non-tumorous tissues, we found a higher level of EIF3H, IGF2BP2, IGF2BP3, KIAA1429 in all six pancreatic tumor tissues, LRPPRC was overexpressed in five pancreatic tumor tissues, while the expression of METTL3 decreased in four pancreatic tumor tissues." (PMID 34332578, 2021).
type 2 diabetes (55 papers, 2008 to 2025). "Genome-wide association studies (GWASs) have identified a cluster of SNPs within the second intron of IGF2BP2 as being associated with type 2 diabetes (T2D)." (PMID 40084251, 2025). "Associations of six polymorphisms of the IGF2BP2 gene such as rs4402960, rs1470579, rs7640539, rs71320321, rs1374910, and rs6769511 with type 2 diabetes have been discovered and subsequently replicated by independent studies." (PMID 36902173, 2023). "Analysis of genome-wide association studies reveals a specific association of lncRAP2 and Igf2bp2 polymorphic alleles with increased body fat and greater risk of type 2 diabetes." (PMID 35036870, 2022). "Among lncRAP2 interactors, Igf2bp2 regulates adipocyte function via posttranscriptional control of metabolically important proteins, impacting sensitivity to diet-induced obesity and type 2 diabetes risk." (PMID 35036870, 2022). "Phenome-wide association studies reveal specific associations of genetic variants within both lncRAP2 and Igf2bp2 with body mass and type 2 diabetes, and both lncRAP2 and Igf2bp2 are suppressed in adipose depots of obese and diabetic individuals." (PMID 35036870, 2022). "IGF2BP2 is associated with type 2 diabetes mellitus (T2DM) and obesity and has been reported to be involved in insulin resistance, lipid metabolism and tumorigenesis." (PMID 35293050, 2022). "Recent genome-wide association studies (GWAS) have revealed that IGF2BP2 gene induces the development of type 2 diabetes (T2D) by disrupting insulin secretion." (PMID 33568150, 2021). "Genome-wide association studies (GWASs) have not identified any potential IGF2BP1 single-nucleotide polymorphisms (SNPs) linked to human disease whereas SNPs in the second intron of IGF2BP2 are associated with type 2 diabetes." (PMID 32154328, 2020). "IGF2BP2 was detected in a genome‐wide association study targeting type 2 diabetes in humans, and attention has recently been paid to this gene." (PMID 32607209, 2020). "IGF2BP2 is an important gene associated with type 2 diabetes, and a recent study found that Igf2bp2−/− mice were lean and resistant to diet-induced obesity." (PMID 29339719, 2018). "Recent genome-wide studies suggest IGF2BP2 as a susceptibility gene for human type 2 diabetes mellitus (T2DM), and a single nucleotide polymorphism (SNP, rs4402960) in the second intron is associated with T2DM." (PMID 29736175, 2018). "The IGF2BP2 rs4402960 polymorphism, which conveys an increased risk of type 2 diabetes, also increases the risks of colon and breast cancer according to the results from independent studies." (PMID 29736175, 2018). "Polymorphisms within intron 2 of the Igf2bp2 gene influence type 2 diabetes risk and have been linked to reduced early phase insulin release and other indices of impaired pancreatic beta cell function." (PMID 22427968, 2012). "Previous studies showed that IGF2BP2 is a type 2 diabetes-associated gene." (PMID 40641925, 2025). "IMP2 (or known as IGF2BP2) is a reader of N6-methyladenosine to regulate mRNA stability and translation, despite the fact its intronic SNP is well known in association with genetic predisposition of type-2 diabetes." (PMID 36831329, 2023). "IGF2BP2 is associated with impaired insulin secretion and human type 2 diabetes." (PMID 37373054, 2023). "Variants in IGF2BP2 have been previously found to be significantly associated with alterations in insulin secretion and resistance, and IGF2BP2 was found upregulated in the β-cells of patients with type 2 diabetes." (PMID 35761192, 2022). "Moreover, SNP rs4402960 in the IGF2BP2 gene, which encodes insulin-like growth factor 2 mRNA-binding protein 2, is significantly associated with an increased risk of type 2 diabetes." (PMID 35761192, 2022). "Previously, IGF2BP2 was thought to be a type 2 diabetes (T2D)-associated gene." (PMID 33568150, 2021).
type 2 diabetes (continued). "Many of these target genes were linked to type 2 diabetes and beta cell functions, with the Insulin -like Growth Factor 2 mRNA Binding Protein 2 (Igf2bp2) gene, encoding the insulin-like growth factor 2 mRNA binding protein 2, being one of the most downregulated by the H3K4me3 loss." (PMID 33919851, 2021). "The Igf2bp2 gene has been identified as a type 2 diabetes susceptibility locus." (PMID 22427968, 2012). "Notably, genetic variants of IGF2BP2 are associated with type 2 diabetes and metabolic phenotypes." (PMID 40632859, 2025). "In the context of the Women’s Interagency HIV Study (WIHS) research, the identification of IGF2BP2 as a significant determinant in antiretroviral therapy has revealed its capacity to modulate the genetic impacts of established risk variants linked to type 2 diabetes." (PMID 38601162, 2024). "The objective of this study was to systematically evaluate the contribution of the insulin-like growth factor 2 mRNA-binding protein 2 (IGF2BP2) to type 2 diabetes mellitus (T2DM) and its interaction with obesity to T2DM susceptibility." (PMID 25062844, 2014). "Polymorphisms of TCF7L2, IGF2BP2, CDKAL1, KCNQ1, and PPARG genes showed a strong contribution to type 2 diabetes." (PMID 36902173, 2023). "Insulin-like growth factor 2 mRNA-binding protein 2 (IGF2BP2) is considered as genetic loci related to increased threat to diabetes type 2, as well as participating in lipid metabolism and insulin production." (PMID 35552417, 2022). "Multiple studies have highlighted that IGF2BP2 plays a significant role in metabolism of type 2 diabetes and cancer." (PMID 34258163, 2021). "Second, insulin-like growth factor 2 mRNA-binding protein 2 (IGF2BP2 or IMP2) is functional during embryonal development, it is linked with susceptibility to type 2 diabetes and participates in the maintenance of CSCs." (PMID 33810170, 2021). "A major member of the IGF family of growth factors, IGF2, is regulated by IGF2BP2 posttranscriptionally and commonly dysregulated in type 2 diabetes along with IGF2BP2 itself." (PMID 29736175, 2018). "For example, the variation in the IGF2BP2 (rs4402960) has been reported to enhanced the effect of repaglinide treatment in type 2 diabetes patient in China." (PMID 27090252, 2014). "The association of Insulin-like growth factor 2 mRNA-binding protein 2 (IGF2BP2) common variants (rs4402960 and rs1470579) with type 2 diabetes (T2D) has been performed in different populations." (PMID 23029108, 2012). "We confirmed the effects of SNPs from PPARG, KCNJ11, CDKAL1, CDKN2A-CDKN2B, IDE-KIF11-HHEX, IGF2BP2 and SLC30A8 on risk for type 2 diabetes, with odds ratios ranging from 1.114 to 1.406 (P value range from 0.0335 to 1.37E-12)." (PMID 19862325, 2009). "In conclusion, we confirmed the association between PPARG, KCNJ11, CDKAL1, CDKN2A-CDKN2B, IDE-KIF11-HHEX, IGF2BP2, SLC30A8 variants and type 2 diabetes." (PMID 19862325, 2009). "Previously, the role of IGF2BP2 was thought to be limited to genes involved in type 2 diabetes." (PMID 38443392, 2024). "For seven of overall 17 potential target genes, we found studies reporting a role in CVD, comprising HF and cardiac remodeling after MI (Ccnd2, Pde1c, Ddah1), atherosclerosis (Igf1r), blood pressure and hypertension (Fign, Efnb3), and type 2 diabetes (Igf2bp2)." (PMID 35332188, 2022). "We show that the known loci for HbA1c, such as ABCB11, and the established type 2 diabetes loci, IGF2BP2, and ARAP1, could mediate their effect on type 2 diabetes risk by their action on pancreatic beta-cell glucose sensitivity." (PMID 32944759, 2021). "After correction for multiple testing, type 2 diabetes–associated SNPs in or near HHEX, CDKAL1, IGF2B2, fasting glucose–associated SNPs in or near CDKAL1 and IGF2BP2, and a 2-hour glucose post-OGTT–associated SNP at the GIPR locus were all associated with beta-cell glucose sensitivity." (PMID 32944759, 2021). "Studies have indicated the involvement of IGF2BP2 in type 2 diabetes in humans." (PMID 33228033, 2020).
type 2 diabetes (continued). "Previous studies have shown the involvement of IGF2BP2 gene polymorphism in attenuating the first phase of glucose-stimulated insulin secretion based on hyperglycaemic clamps, and the regulation of pancreatic β-cell function in Type 2 diabetes mellitus (T2DM) patients." (PMID 32662505, 2020). "Notably, type 2 diabetes and multiple cancers share common genetic fingerprints in the IGF2BP2 gene." (PMID 29736175, 2018). "A majority of genes associated with type 2 diabetes from this meta-analysis (ADCY5, CDKAL1, CDKN2A/B, HHEX, IGF2BP2, SLC30A8, TCF7L2 and KCNQ1) are involved in pancreatic beta cell function, while two are implicated in insulin sensitivity (PPARG) and adiposity (FTO)." (PMID 25145545, 2014). "Polymorphisms in the Igf2bp2 gene are associated with risk of developing type 2 diabetes, but detailed functional characterisation of IGF2BP2 protein is lacking." (PMID 22427968, 2012). "Most of the genes associated with type 2 diabetes (TCF7L2, SLC30A8, HHEX, CDKAL1, CDKN2A/B and IGF2BP2) might be implicated in beta cell function." (PMID 20161779, 2010). "In addition, SNPs from PPARG, KCNJ11, CDKAL1, IDE-KIF11-HHEX, IGF2BP2 and SLC30A8 were also moderately associated with type 2 diabetes, with ORs ranging from 1.114 to 1.282 (P<0.05)." (PMID 19862325, 2009). "Compared with IGF2BP1 and IGF2BP3, IGF2BP2 has been considered as a candidate gene for type 2 diabetes mellitus (T2D)." (PMID 36237306, 2022). "In addition, IGF2BP2 and GCKR have been identified by several meta-analyses as risk genetic variants for Type 2 Diabetes with effects in WHR." (PMID 25852736, 2015). "However, in 2007, several reproducible genome-wide association studies (GWASs) confirmed these well-established susceptibility genes and identified a number of new loci (SLC30A8, HHEX, CDKN2A/B, IGF2BP2, GCKR, FTO, and CDKAL1) at which common variants influence risk of type 2 diabetes in Europeans." (PMID 20161779, 2010). "IGF2BP2 also directly binds to PDX1 in an m6A-dependent manner and promotes pancreatic β-cell proliferation in type 2 diabetes." (PMID 35047491, 2021). "For example, two genotypes linked with the susceptibility of Type 2 Diabetes Mellitus (T2DM); rs7903146 SNP in the TCF7L2 gene [OMIM: 125853], a heterozygous modifier affecting drug response, and the rs4402960 SNP in IGF2BP2 gene [OMIM: 125853] a heterozygous risk factor modifier." (PMID 31604968, 2019). "Recently, several genome-wide and candidate gene association studies have identified many novel genetic loci for type 2 diabetes (T2D); among these genes, CDKAL1, IGF2BP2, SLC30A8, CDKN2A/B, HHEX, FTO, TCF2, KCNQ1, and WFS1 are the most important." (PMID 20509872, 2010). "The current study confirmed the association between PPARG, KCNJ11, CDKAL1, CDKN2A-CDKN2B, IDE-KIF11-HHEX, IGF2BP2 and SLC30A8 and type 2 diabetes." (PMID 19862325, 2009). "In this study, we confirmed the effects of variations in PPARG, KCNJ11, CDKAL1, CDKN2A-CDKN2B, IDE-KIF11-HHEX, IGF2BP2 and SLC30A8 on type 2 diabetes." (PMID 19862325, 2009). "However, after correction of multiple comparisons, only the association between SNPs from CDKAL1, CDKN2A-CDKN2B, IDE-KIF11-HHEX, IGF2BP2 and SLC30A8 and type 2 diabetes remained to be significant." (PMID 19862325, 2009). "The region on Chr C2 near SNPs 5 and 6, contained four known genes (TRA2B, CHCHD4, IGF2BP2 and SENP2) but none of these genes contained disease-associated protein-coding changes, despite TRA2B and IGF2BP2 having association with type 2 diabetes in other species." (PMID 33228033, 2020).
breast cancer (46 papers, 2017 to 2025). A primary or metastatic malignant neoplasm involving the breast. "IGF2BP2 overexpression was associated with decreased cell adhesion and migration in breast cancer cells." (PMID 34239534, 2021). "IGF2BP2 can be particularly informative for basal-like breast cancer, a subtype mostly associated with triple-negative breast cancer, which generally has a poor survival." (PMID 29736175, 2018). "The T2DM-relevant SNP rs4402960 in IGF2BP2 gene increases the risk of breast cancer in at least some ethnic groups." (PMID 29736175, 2018). "We further analyze two independent breast cancer datasets and find that specific isoforms of IGF2BP2, NECTIN4, ITGB6, and KLHDC9 are significantly associated with AZD6244, lapatinib, erlotinib, and paclitaxel, respectively." (PMID 29066719, 2017). "IGF2BP2 rs4402960 increases the risk of developing breast cancer in female Chinese Hans." (PMID 33568150, 2021). "Consequently, over-expression of IGF2BP2 is not only a potential biomarker for developing breast cancer but also a novel diagnostic factor for the same disease." (PMID 33568150, 2021). "Our findings revealed that knockdown of IGF2BP2 also effectively suppressed the growth of breast cancer cells in tumorspheres." (PMID 40347943, 2025). "RPPH1 enhances breast cancer progression by stabilizing m6A-modified FGFR2 mRNA via IGF2BP2, activating PI3K/AKT signaling." (PMID 40565315, 2025). "Functionally, LINC01133 inhibited the metastatic ability of ER+ breast cancer via mediating the IGF2BP2 stability via a ubiquitination-dependent manner." (PMID 40641925, 2025). "This study aimed to explore the mechanism of insulin‐like growth factor 2 mRNA‐binding protein 2 (IGF2BP2) affecting the proliferation of breast cancer (BC) cells." (PMID 39969065, 2025). "For instance, upregulation of IGF2BP2 results in shorter survival and poorer prognosis for patients with breast cancer, esophageal carcinoma, and hepatocellular carcinoma." (PMID 40641925, 2025). "In this study, we found that LINC01133 interacted with IGF2BP2 to inhibit its degradation mediated by ubiquitination, which promoted the deterioration of ER+ breast cancer." (PMID 40641925, 2025). "We further analyzed the methylation status of IGF2BP2 promoter region in different breast cancer subtypes, and found that the methylation level of IGF2BP2 promoter region in TNBC was lower compared with that in other molecular subtypes." (PMID 37983610, 2024). "In the present study, we found that GAS5 suppressed the growth of breast cancer cells by interacting with IGF2BP2." (PMID 38782769, 2024). "GAS5 regulated by FTO-mediated m6A modification represses the growth of breast cancer via the IGF2BP2/QKI pathway, suggesting that the FTO/GAS5/IGF2BP2/QKI pathway can be a potential target for breast cancer treatment." (PMID 38782769, 2024). "Recent experimental data underscore a connection between IGF2BP2 and the development of various cancers, including hepatocellular carcinoma, breast cancer, ovarian cancer, colon cancer, and esophageal cancer." (PMID 39711402, 2024). "GAS5 suppressed breast cancer growth via IGF2BP2/QKI, and this inhibitory effect was modulated by FTO both in vitro and in vivo." (PMID 38782769, 2024). "Then we amplified the IGF2BP2 promoter methylated and unmethylated fragments in 8 breast cancer cell lines by PCR and detected by agarose gel electrophoresis." (PMID 37983610, 2024). "For example, miR-1193 activates ERK and PI3K/Akt signaling pathways by binding to the 3’ UTR of the IGF2BP2 mRNA to inhibit the proliferation and invasion of breast cancer cells." (PMID 35299748, 2022). "Recent evidence has indicated that IGF2BP2 contributes to the progression of several cancers, including liver cancer, breast cancer, ovarian cancer, etc." (PMID 35717493, 2022).